ANXA1 (annexin A1)
Diseases named in the same sentence as ANXA1 in open-access papers (continued):
Sharing a sentence is not in itself a finding about the gene and the disease.
lymph node metastasis (11 papers, 2012 to 2025). "A univariate Cox regression model revealed that age, tumor depth, lymph node metastasis, distant metastasis, clinical stage, and ANXA1 expression were associated with the prognosis of BLCA patients in terms of OS." (PMID 34991599, 2022). "Nevertheless, ANXA1 overexpression leads to GS invasion as well as lymph node metastasis, and it is linked with prognostic factors such as venous and lymphatic invasions and advanced stages of GC." (PMID 32099594, 2019). "The loss of annexin A1 expression has been significantly associated with advanced stage lymph node metastasis, an advanced disease stage, and poor histological differentiation." (PMID 24209905, 2013). "In CRC, ANXA1 is associated with invasion and lymph node metastasis." (PMID 36077674, 2022). "ANXA1 overexpression was also related not only to TNBC but also to lymph node metastasis." (PMID 41283264, 2025). "Additionally, ANXA1 expression may be correlated with lymphatic invasion (p = 0.011), venous invasion (p = 0.023), and lymph node metastasis (p = 0.042) in CRC patients, suggesting its potential role in tumor invasion and lymph node metastasis." (PMID 41283264, 2025). "Interestingly, ANXA1 expression did not correlate to any of patients' clinical features, e.g., age group, sex, lymph node metastasis, or degree of differentiation, which makes ANXA1 rather an independent prognostic marker than a specific marker to a certain group of patients." (PMID 33959206, 2021).
multiple sclerosis (11 papers, 2009 to 2026). A progressive autoimmune disorder affecting the central nervous system resulting in demyelination. "In Multiple Sclerosis, the loss of ANXA1 expression has been identified at brain parenchymal capillaries of patients." (PMID 29614751, 2018). "Elevated ANXA1 levels were identified in the white matter and sclerotic plaques in the brains of patients with multiple sclerosis." (PMID 38639785, 2024). "For instance, in multiple sclerosis (MS), increased expression of ANXA1 has been observed in macrophages at the sites of active lesions." (PMID 35146757, 2022). "In this study, we investigated the potential modulatory role of Annexin A1 in the development of experimental autoimmune encephalomyelitis, a model of multiple sclerosis." (PMID 19912648, 2009). "In conclusion, this study presents novel evidences of pivotal roles for AnxA1 in a mouse model of multiple sclerosis." (PMID 19912648, 2009). "It was proposed that increased levels of ANXA1 in patients with multiple sclerosis might demonstrate an ineffective attempt to overcome chronic inflammation." (PMID 38639785, 2024). "ANXA1 might therefore be a promising therapeutic addition in the treatment of patients with multiple sclerosis and in correcting BBB function." (PMID 38639785, 2024). "Future studies on the identification and generation of neutralizing antibodies against AnxA1, currently under development, will provide us the opportunity to validate novel therapeutic approaches for the treatment of multiple sclerosis that target AnxA1 expression or function." (PMID 19912648, 2009). "In agreement with this hypothesis, previous studies have shown an increase in AnxA1 content in post-mortem CNS tissue samples from MS patients, in particular in the diseased white matter as well as in multiple sclerosis plaque tissue." (PMID 19912648, 2009). "Furthermore strategies aiming at reducing Annexin A1 functions or expression in T cells might represent a novel therapeutic approach for multiple sclerosis." (PMID 19912648, 2009).
oral squamous cell carcinoma (11 papers, 2013 to 2025). "ANXA1 nuclear translocation has also been negatively associated with the survival of patients with oral squamous cell carcinoma and gastric adenocarcinoma." (PMID 29614751, 2018). "Dysregulation and altered localization of ANXA1 have been correlated with tumor development and progression in several cancers including oral squamous cell carcinoma and gastric adenocarcinoma." (PMID 33261560, 2020). "Similarly, reduced Annexin-A1 expression is reported in oral squamous cell carcinoma and that its expression negatively correlated with the pathologic differentiation grades of tumors." (PMID 37954869, 2023). "Conversely, particular cancers are more prone to develop in downregulated states of ANXA1 expression including cancers such as prostate, cervical, lymphoma, oesophageal, larynx, nasopharyngeal and oral squamous cell carcinoma." (PMID 29614751, 2018).
peritonitis (11 papers, 2015 to 2025). Inflammation of the peritoneum (tissue that lines the abdominal wall and covers most of the organs in the abdomen). "Similar findings have been reported in other chronic inflammatory models, where ANXA1-deficient animals exhibited exacerbated inflammatory responses in carrageenan-induced edema and zymosan-induced peritonitis models, with increased leukocyte migration and IL-1β production." (PMID 41200163, 2025). "In models of air-pouch and zymosan-induced peritonitis, the anti-migratory properties of AnxA1 and Ac2-26 were attenuated in Fpr2−/− mice." (PMID 28809781, 2017). "Similar results were obtained for mesenteric mast cells in CV-induced peritonitis, and we detected high endogenous levels of AnxA1 in these cells at 4 and 24 hours." (PMID 26147724, 2015). "Taken together, our results confirm that neutrophils and mast cells represent important sources of AnxA1 in the tissues and thereby contribute to the regulation of inflammatory responses triggered by CV and MjTX-II-induced peritonitis." (PMID 26147724, 2015). "The effect of the N-terminal peptide Ac2-26 of AnxA1 on the toxic activities of Bothrops moojeni crude venom (CV) and its myotoxin II (MjTX-II) were evaluated using a peritonitis rat model." (PMID 26147724, 2015). "We next investigated whether endogenous ANXA1 played a similar role during more complex inflammatory settings, using zymosan-induced peritonitis as a typical resolving inflammatory response." (PMID 26101324, 2015). "We demonstrate temporal increases in annexin A1 (AnxA1) protein and mRNA levels in peritoneal lavage fluid (PLF), peritoneal macrophages, and spleen in a murine model of zymosan-induced acute peritonitis." (PMID 35327639, 2022).
squamous cell carcinoma (11 papers, 2013 to 2024). A carcinoma arising from squamous epithelial cells. "However, recent studies indicate loss of function of ANXA1 in squamous cell carcinomas of the esophagus and head and neck, as well as in adenocarcinomas of the prostate and breast." (PMID 33291071, 2020). "Our work also corroborated with this hypothesis since ANXA1 protein expression was significantly increased in high-risk HPV squamous cell carcinoma of penis samples independently of the subtype of penile squamous cell carcinoma compared to the HPV negative squamous cell carcinoma of penis samples." (PMID 23341933, 2013). "We infer that the E. tirucalli latex contributes to increased expression of the gene ANXA1 in the larynx squamous cell carcinoma, confirming the role of Annexin A1 in the regulation of cell proliferation, besides the anti-inflammatory function." (PMID 27209356, 2016). "Squamous cell carcinoma of esophagus showed a significant reduction of ANXA1 mRNA and protein expression, which is strongly expressed in the normal squamous epithelium." (PMID 25038797, 2014). "Taken together, the concept that ANXA1 is “a tumor suppressor” and therefore is usually down-regulated in squamous cell carcinoma can be identified." (PMID 25038797, 2014). "Various other studies have corroborated these findings, showing a reduction of ANXA1 expression in squamous cell carcinomas of the head and neck and revealing a relationship between this reduction and a lack of differentiation in the tumors." (PMID 24782913, 2014). "We found that Hsp90, Annexin A1, and HMGB1 were largely released in the extracellular medium in response to either 1 or 10 μM OR141 in SCC7 and A431 squamous cell carcinoma cells." (PMID 31508370, 2019). "We observed a reduction in the expression of ANXA1-TYR in cancers compared to the epithelia in both the HPV + and HPV- samples, a finding that contrasts with the data reported in a recent study of squamous cell carcinoma of the cervix." (PMID 24782913, 2014). "Thus, in terms of translational value, Annexin-A1 expression may help delineate HPV-negative keratin-forming vs. HPV-positive non-keratinizing forms of squamous cell carcinoma." (PMID 37954869, 2023).
esophageal squamous cell carcinoma (10 papers, 2008 to 2024). Esophageal squamous cell carcinoma (ESCC) is a type of esophageal carcinoma (EC) that can affect any part of the esophagus, but is usually located in the upper or middle third. "An increased presence of ANXA1 in cell nuclei is considered a significant predictor of poor overall survival in oral and esophageal squamous cell carcinoma." (PMID 38893148, 2024). "In esophageal squamous cell cancer, the levels of Annexin A1 (ANXA1), which is secreted by epithelial cells, decrease as the tumor advances." (PMID 37686288, 2023). "Recently, annexin A1 translocation was noted in esophageal squamous cell carcinoma." (PMID 18637184, 2008). "It has been reported that serum ANXA1 levels increased after chemoradiotherapy in esophageal squamous cell carcinoma (ESCC) patients." (PMID 36247003, 2022). "In the esophageal squamous cell carcinomas, ANXA1 mRNA expression was 6-fold lower than in the noncancerous colon tissue." (PMID 25038797, 2014).
inflammatory bowel disease (10 papers, 2012 to 2025). A spectrum of small and large bowel inflammatory diseases of unknown etiology. "In inflammatory bowel disease (IBD), loss of Annexin A1 expression likely promotes inflammatory status, while an enhanced level of Annexin A1 may be predictive of the effectiveness of the therapeutic intervention." (PMID 35563776, 2022). "Our data indicate that assessing intestinal expressions of formyl peptide receptors and annexin A1 might provide precious information on the disease activity and responsiveness to infliximab in inflammatory bowel disease patients." (PMID 34603288, 2021). "Raised levels of ANXA1 autoantibodies have also been seen in patients with inflammatory bowel disease and systemic lupus erythematosus (SLE), particularly in lupus nephritis [76, 77, indicating a potential role for ANXA1 on B cells in these diseases." (PMID 35146757, 2022). "Particular focus has been placed on macrophages as it was noticed, in biopsies from patients with inflammatory bowel disease (IBD), that ANXA1 localisation is higher in macrophages during disease resolution compared to active disease where instead ANXA1 expression is greater in neutrophils." (PMID 29614751, 2018). "Annexin A1 (ANXA1) inhibits NF-κB, a key regulator of inflammation, the common pathophysiological mechanism of inflammatory bowel diseases (IBD)." (PMID 22844504, 2012).
type 2 diabetes (10 papers, 2015 to 2023). "Plasma ANXA1 is increased in patients with type 2 diabetes compared to normoglycemic controls and is positively correlated with degree of metabolic impairment." (PMID 37208759, 2023). "Further, treatment with Ac2-26 attenuated kidney injury in db/db mice (a genetic model of type 2 diabetes) and in diabetic Annexin A1 knockout mice." (PMID 34943928, 2021). "We and others have shown that the plasma levels of ANXA1 are elevated in patients with long-standing type-1 diabetes (over 25 years from diagnosis) and those with type-2 diabetes and obesity compared to age-matched healthy controls." (PMID 31114582, 2019). "Plasma ANXA1 positively correlated with fatty liver index and elevated plasma cholesterol in patients with type-2 diabetes, suggesting a link between aberrant lipid handling, and ANXA1." (PMID 30972066, 2019). "We demonstrate that patients with type-2 diabetes have increased plasma levels of ANXA1 when compared to normoglycemic subjects." (PMID 30972066, 2019). "Interesting, serum ANXA1 levels in patients with type 1 and type 2 diabetes did not correlate with increased systemic inflammation (C-reactive protein levels)." (PMID 31114582, 2019).
brain tumor (9 papers, 2013 to 2025). "Understanding the role of ANXA1 in GBM-derived EV is important in determining the influence of EV on the brain tumour microenvironment and role in tumour cell invasion." (PMID 27770278, 2017). "Of note, ANXA1, ANXA2, GNAS, HSP90AA1, HSP90AB1 and PSMD2, were highly abundant in EVs captured from GBM neurosurgical aspirates and in Pre-OP GBM uEVs here, implicating a potential brain tumour diagnostic utility for TRiC subunits and their interacting partners." (PMID 38212481, 2024). "As gene expression data indicates ANXA1 overexpression in brain malignancies and our immunohistochemistry for the Anxa1 N-terminal domain showed strong signals in brain tumours, the IF7C(RR)-SN38 conjugate may be clinically relevant to treatment of brain tumours in humans." (PMID 32921792, 2020).
chronic obstructive pulmonary disease (9 papers, 2015 to 2023). A chronic and progressive lung disorder characterized by the loss of elasticity of the bronchial tree and the air sacs, destruction of the air sacs wall, thickening of the bronchial wall, and mucous accumulation in the bronchial tree. "In welders, we found an increase of Annexin A1 (AnxA1), also called Lipocortin I. AnxA1 is increased in plasma of patients with chronic obstructive pulmonary disease, and in vitro cigarette smoke causes increased levels and an effect on lung fibroblast function." (PMID 34464420, 2021). "Furthermore, increased serum ANXA1 has been identified in patients with chronic obstructive pulmonary disease (COPD) compared to healthy controls." (PMID 35146757, 2022). "Annexin A1 and its derivative peptides have been shown to have therapeutic effect in various disease states, including sepsis, lung inflammation and chronic obstructive pulmonary disease (COPD), myocardial infarction, and intestinal wound repair." (PMID 34566657, 2021).
head and neck squamous cell carcinoma (9 papers, 2017 to 2026). A squamous cell carcinoma that arises from any of the following anatomic sites: lip and oral cavity, nasal cavity, paranasal sinuses, pharynx, larynx, and salivary glands. "The protein annexin A1 (ANXA1) is downregulated in head and neck squamous cell carcinoma (HNSCC), correlated with pathological differentiation grade." (PMID 40227604, 2025). "Nonetheless, while Annexin-A1 expression is reportedly increased in some tumors (e.g., gut, esophagus, lung, etc.), its expression is seemingly lost in other tumors such as head and neck squamous cell carcinoma (HNSCC)." (PMID 37954869, 2023). "Annexin1A (ANXA1), increased by Onco-P20, has been proposed as a tumor suppressor in head and neck squamous cell carcinomas." (PMID 34073987, 2021). "Annexin A1 (ANXA1) down-regulation is an early and frequent event in the development of head and neck squamous cell carcinomas (HNSCC)." (PMID 28754915, 2017). "Researchers have concluded that ANXA1 acts as a tumour suppressor in head and neck squamous cell carcinoma (HNSCC) and could be an important prognostic biomarker." (PMID 32742772, 2020). "As both ANXA1 and ANXA2 have been found down-regulated in head and neck squamous cell carcinoma, it was of special interest to determine whether ANXA9 showed a similar pattern of expression as this might relate to common features in the evolution, structure and function of these clade members." (PMID 30744186, 2019).
colorectal adenocarcinoma (8 papers, 2013 to 2025). The most common type of colorectal carcinoma. "In another study, the impact of punicalagin (PU) on the interplay between autophagy and apoptosis in HCT 116 colorectal adenocarcinoma cells is analyzed through the regulation of Annexin A1 (Anx‐A1) expression." (PMID 40018013, 2025). "In keeping with these findings, expression of annexin A1 strongly correlated with S100-A11 expression in the Tissue Cancer Genome Atlas data set of colorectal adenocarcinoma patients, both at mRNA and protein levels." (PMID 31545917, 2019). "The cBioPortal software demonstrated that annexin A1 predicted colorectal adenocarcinoma prognosis with a borderline significance (P = 0.07)." (PMID 31545917, 2019). "Hence, this study aimed to investigate the role of PU in modulating the interplay between apoptosis and autophagy by regulating Annexin A1 (Anx-A1) expression in HCT 116 colorectal adenocarcinoma cells." (PMID 32823596, 2020). "In breast epithelial tumor cells, the signaling elicited by ANXA1/FPR2 interaction induces an increased level of cyclin D1, which is associated to the activation of the PI3K/Akt/p70S6K pathway, and in SKCO-15 colorectal adenocarcinoma, ANXA1 mediates cell invasion via FPR2." (PMID 23549262, 2013). "More recent studies have shown that the ANXA1 N-terminal peptide, Ac2-26, promotes the migration of WS1 human skin fibroblasts and the invasion of SKCO-15 colorectal adenocarcinoma cells through interaction with FPRs." (PMID 36414640, 2022).
hairy cell leukemia (8 papers, 2008 to 2025). Hairy cell leukemia (HCL) is a rare type of leukemia in which abnormal B-lymphocytes are present in the bone marrow, spleen and peripheral blood. "Hairy cell leukemia markers (Annexin A1, DBA44, TRAP) were investigated to exclude the very remote possibility of evolution from hairy cell leukemia (in consideration of the clinical setting)." (PMID 23285191, 2012). "Based on CD 20, PAX5, and CD 79b, a possible diagnosis of hairy cell leukaemia was made and annexin A1 IHC was recommended because it was not available in our hospital's setup." (PMID 37538441, 2023). "Lack of ANXA1 in hairy cell leukemia resulted in tumor aggressiveness." (PMID 39588389, 2024). "In order to exclude lymph node involvement by hairy cell leukemia (HCL), all BRAF mutant NMZL were carefully reevaluted and stained for CD103 and Annexin A1 and turned out to be negative; in addition, all of them were negative for cyclin D1." (PMID 29556019, 2018).
influenza (8 papers, 2017 to 2024). An acute viral infection of the respiratory tract, occurring in isolated cases, in epidemics, or in pandemics; it is caused by serologically different strains of viruses (influenzaviruses) designated A, B, and C, has a 3-day incubation period, and usually lasts for 3 to 10 days. "Of them, many had relevance in influenza infection such as genes responsible for virus entry (Anxa1/2, Cd14), interferon signaling (Dusp10, Tnfsf13), or prostaglandin synthesis (Ptgs1/2)." (PMID 35629310, 2022). "Transcription factor XBP1 and serine threonine kinase STK11, which are also dependent on ANXA1 for expression after influenza infection, have both been shown to be important in the regulation of autophagy." (PMID 32512864, 2020). "Annexins are the most enriched cellular proteins of the virions; among them, annexin A1 (ANXA1) contributes to the virulence of influenza." (PMID 29738458, 2018). "It is also possible that during influenza, Annexin A1 activation of FPR2 leads to pro-inflammatory signaling." (PMID 28928730, 2017). "This is of notable interest, as while it has been put forward as a potential target for influenza infection due to its role in virion internalization and persistence, this is the first report of a protozoan parasite exploiting the ANXA1/FPR2 axis to establish greater infection." (PMID 39076982, 2024). "In addition, it cannot be excluded that Annexin A1 adopts a specific structural conformation at the surface of influenza virions or heterodimerize in an unusual fashion, thereby promoting FPR2 pro-inflammatory functions." (PMID 28928730, 2017).